TNF (tumor necrosis factor)
Diseases named in the same sentence as TNF in open-access papers (continued):
Sharing a sentence is not in itself a finding about the gene and the disease.
cancer (continued). "The results showed that Ssd alone would not induce the expression of COX-2 and VEGF in both cancer cell types; however, these genes expression was significantly increased in response to TNF-α treatment, while treatment of Ssd was able to inhibit the TNF-α-mediated expression of COX-2 and VEGF." (PMID 23573150, 2013). "Tumor necrosis factor (TNF), TNF-related apoptosis inducing ligand (TRAIL), Fas-ligand (Fas-L), TNF-related factor-1 and 2 (Traf1/2) etc. are some of the key molecules that belong to the extrinsic pathway or death receptor signaling that are known to be de-regulated in cancers." (PMID 22974127, 2012). "We cannot exclude a diagnosis bias: in the absence of blinding, patients on TNF antagonists may have been screened more accurately for cancers than other patients." (PMID 23155441, 2012). "Two other drugs, Etanercept (a dimeric fusion protein commonly used for the treatment of rhematoid arthritis) and infliximab (a monoclonal antibody against TNFα), have also been met with limited success in clinical trials, showing no improvement in cancer patients suffering from cachexia." (PMID 21832306, 2011). "For instance, they are involved in defense against many viruses, could be either protective or detrimental during non-viral pathogens, act in cancer surveillance, but they are also effector molecules in toxic shock elicited by LPS and TNF." (PMID 21494554, 2011). "The role of TNF α in pathogenesis of malignant tumors is not clearly understood." (PMID 20640152, 2010). "Furthermore, the networks related to cell cycle, cancer and nervous system development and function showed that several genes such as Nfkb2, NFκBia, BRCA1, Vegf, Jag2, Notch1, EGR1, FoxS1 and collagen type I were regulated by TNF." (PMID 20967264, 2010). "Since other signal transduction pathways could also be involved and TNF could be acting indirectly through prostaglandins, which also mediate VEGF-C transcription in cancer cells, future studies are needed to elucidate the mechanisms of inflammation-induced VEGF-C expression in OCPs." (PMID 17997858, 2007). "Consequently, the original aim was to investigate how the apoptosis signaling network was activated in response to different levels of TNF, EGF and insulin and how such differential activation contributes to antagonistic cellular decisions, such as cell death versus survival in cancer cells." (PMID 17559646, 2007). "Consequently, these signals might be potential targets for further biological investigation on how different doses and treatment conditions with TNF, EGF or insulin lead to different death/survival decisions in cancer cells." (PMID 17559646, 2007). "In addition, oncogenic signals such as epidermal growth factor receptor (EGFR) activation, certain and TH1 cytokines such as IFN-γ and TNF-α also induce its expression in cancer cells as well as in non-cancer cells (such as fibroblasts and myeloid cells) in the TME." (PMID 40109334, 2025). "Additionally, these 318 EC-related differentially expressed ARGs were notably enriched in several cancer-related pathways, including pathways in cancer, PI3K-Akt signaling, MAPK signaling, FoxO signaling, apoptosis, cellular senescence, IL-17 signaling, and TNF signaling." (PMID 40746552, 2025). "The use of inflammatory parameters, such as IL-6, tumor necrosis factor alpha (TNF-α), and CRP, allows for a simple and rapid evaluation of whether IF effectively reduces chronic inflammation—a factor known to be involved in the initiation and progression of cancers." (PMID 41008741, 2025). "Moreover, cancer cell survival is orchestrated through complex signaling networks: notably, the nuclear factor-κB (NF-κB) and mitogen-activated protein kinase (MAPK) pathways, which can be activated by pro-inflammatory cytokines such as tumor necrosis factor-α (TNF-α)." (PMID 40507823, 2025).
cancer (continued). "In addition, a large number of macrophages recruited by chemokines or ATP can secrete cytokines, such as TNF, into the TME, which can bind to TNFR1 on cancer cells with normal state and initiate a new necroptosis, establishing a positive feedback effect and inhibiting cancer progression." (PMID 38652105, 2024). "Agents that inhibit the effects of cytokines and growth factors such as TNFα, TGFβ, VEGF, and HGF, all involved in the increase of vascular permeability, decrease transepithelial/endothelial resistance and increase paracellular permeability, could be a useful tool against cancer metastasis." (PMID 39035739, 2024). "The CESAME study group published the results of a prospective assessment examining the risk of new or recurrent cancer in IBD patients with a history of cancer, whether or not they were receiving immunosuppressants such as thiopurines, methotrexate (MTX), or TNF inhibitors." (PMID 39272800, 2024). "Moreover, long-term hyperglycemia leads to the production of pro-inflammatory factors such as IL-6, TNF- α, and cyclooxygenase-2 (COX-2) which may play a role in cancer development by stimulating oncogene expression, regulating cell cycle, and promoting cancer cell proliferation." (PMID 39410536, 2024). "Inflammatory stimuli such as oxidative stress and treatment with cytokines IFNγ, IL-1α, TNFα have also been found to alter the glycosylation pattern of MUC16 in pancreatic cancer cells, suggesting that MUC16 may play a key role in promoting inflammatory signaling in cancer." (PMID 38361923, 2024). "Furthermore, an ad hoc trial comparing the combined TOFA doses with a TNF inhibitor in a cardiovascular risk-enriched population, highlighted the possibility that the risk of major adverse cardiovascular events (MACE) and cancers was higher with TOFA, as non-inferiority criteria was not achieved." (PMID 38979406, 2024). "Indeed, in all the cancer lines stimulated with IFNα, TRAIL was significantly upregulated at the transcript level, whereas TRAIL upregulation was only mild or not observed upon TNFα stimulation in the different cancer cell lines, which served as negative control." (PMID 36765925, 2023). "Meanwhile, the gene level of matrix metallopeptidase nine and tumor necrosis factor α related to tumor metastasis exhibits a downward trend in SLC25A22-silenced cancer cells, indicating inhibition of GSH synthesis may play a critical role in the treatment of cancer metastasis." (PMID 36970628, 2023). "To investigate whether the same direct relation between the TNF-α signaling pathway via NF-κB and MTX resistance found in primary samples was also observed in vitro in a panel of ALL cell lines, we performed an ssGSEA to identify the differentially expressed Cancer Hallmarks across the cell lines." (PMID 37895229, 2023). "Interleukins, tumor necrosis factor-alpha (TNF-α), transforming growth factor-beta (TGF-β), interferons, and vascular endothelial growth factor (VEGF) are the representative inflammatory cytokines in various cancers, which may promote or inhibit cancer progression." (PMID 36140220, 2022). "However, in cancer cells, TNF-α receptor-1 (TNF-R1), which is expressed in virous tumorous cells including pancreatic cells, was shown to be responsible for transmitting the death signals from the cell surface to the intracellular signaling pathway following the activation of TNF-α." (PMID 35708464, 2022). "Interestingly, BMDC exposed to synchronized ferroptotic cancer cells (early, intermediate, late) in contrast to UVB-treated apoptotic cells did not produce substantial amounts of cytokines related to inflammation (IL-6, IL-12, TNF, IFN-β) and adaptive immune response (IL-10, IFN-γ)." (PMID 35760796, 2022).
cancer (continued). "Consequently, in TP microglia, LTF, the significant TF regulator is found to regulate signaling pathways like TNF, TLR, chemokine, B-cell receptor and processes such as transcriptional misregulation, natural killer cell mediated cytotoxicity, phagocytosis and carbon metabolism in cancer." (PMID 34976314, 2022). "This might be of particular interest in the context of TNF-α non-responsive cancers." (PMID 35406442, 2022). "Indeed, treatment of normal RMF-EG fibroblasts with IL-6 and TNF-α, two abundant cytokines in the conditioned medium of MDA-MB-231 cancer cells, increased KDM2A protein level in a dose-dependent manner suggesting these two cytokines may play a role in stimulating KDM2A expression in fibroblasts." (PMID 33024266, 2021). "Macrophages can produce proinflammatory mediators such as IL-6, TNF, IFN-γ, growth factors, including epidermal growth factor (EGF) and Wnt, proteases, ROS, and nitrogen substances that may produce a mutagenic microenvironment, further facilitating cancer initiation." (PMID 34965886, 2021). "The findings reported here suggest that safranal’s anti-cancer properties could be attributed to its anti-inflammatory activities through downregulation of NF-κB, COX-2, and iNOS expression levels as well as to the reduction of both TNF-α and its receptor TNFR1." (PMID 35177980, 2021). "TNF-β, the closest structural homolog to TNF-α, was identified around 35 years ago and has recently come to attention as it may stimulate NF-κB activation in cancer cells with a similar potency to TNF-α, thereby up-regulating proliferation, invasion and malignancy of cancer cells." (PMID 32244288, 2020). "Several hypotheses in cancer physiopathology assume that lymphoid cell activity is the principal mechanism involved in tumorigenesis inhibition, through cell immunity and secretion of several cytokines such as TNF (tumor necrosis factor) or IFN-γ, the complement system, opsonization, and others." (PMID 32599891, 2020). "Additionally, discreet expression of TNF-α was observed in the cell group not exposed to siRNA, confirming the cytogenetic findings, which described weak participation of this pro-apoptotic protein once the cancer was already established." (PMID 31936364, 2020). "Moreover, TNFα treatment induced PC3 cell migration, but such an effect was blunted upon RHBDL2 silencing, which suggested that this protease might act as downstream effector of the cytokine in the regulation of cancer cell migration." (PMID 31783481, 2019). "However, the effect of PRFR on TNF-α-induced cancer progression has not yet been clarified." (PMID 31540489, 2019). "Therefore, given the observed synergy between SM or TNFα with EZH2 inhibitors such as UNC1999 and GSK343, which are in clinical development, we propose that such combination therapy could be further exploited to target other cancer types." (PMID 30854231, 2019). "Furthermore, CpG-MCA nanohydrogels effectively induced high expression of tumor necrosis factor-α and interleukin-6, and remarkably inhibited the proliferation of U251 cells, suggesting that CpG-MCA nanohydrogels are expected to be employed as the potent anti-cancer immunostimulant." (PMID 31243604, 2019). "Therefore, the TNFα-PD-L1-PD-1 axis may be a new negative feedback loop that occurs between TAMs and cancer cells." (PMID 30062558, 2018). "Moreover, knockdown of p65 by shRNA expression only slightly diminished the amount of cellular Fas indicating that in this cancer cell line Fas expression was not under the control of NFκB and hence TNFα was unable to sensitize the cells to FasL-induced apoptosis." (PMID 30185788, 2018). "However, TNF-α is not always detectable in cancer patients, and concentrations may vary between individuals and throughout the course of the disease." (PMID 25624918, 2015).
cancer (continued). "However, neither NF-κB nor TNF-α has correlation with the clinicopathological features including patient age, histological subtype, age at menarche, menopause, number of pregnancies, number of deliveries, and family history of cancer (P > 0.05, resp)." (PMID 24864130, 2014). "Thus, the implication of TNF-α in cancer cachexia in our murine model was not clear." (PMID 23326296, 2012). "Also, a recent report has suggested that polymorphisms associated with low expression of anti-inflammatory IL-10 and TGF-β1 and immunomodulatory TNF-α, IFN-γ and IL-6 could be involved in the mechanisms of cancer progression and escape from immune surveillance." (PMID 18221542, 2008). "Furthermore, the spreading carcinoma cells may have some capability in escaping the immune surveillance since TNF-α has not been found to induce ICAM-1 and HLA class 1 and 2 antigens in SiHa and CaSki cells." (PMID 18257926, 2008). "As TNF-α enhances CCR6 expression, CCR6+ cells interact with CCL20, facilitating migration in cancer cells but not affecting normal thyroid cells." (PMID 40150133, 2025). "In endothelial cells and monocytes stimulated with TNF-α to mimic sepsis, caprylate enhanced mitochondrial respiration without increasing IL-6 secretion, suggesting that it may influence energy metabolism in cancer and normal tissues without promoting pro-inflammatory signaling." (PMID 41003013, 2025). "NK cells can recognize and destroy cancer cells without the need for prior exposure or activation, by releasing cytotoxic granules and cytokines, such as IFN-γ and TNF-α, which directly induce apoptosis (cell death) in cancer cells." (PMID 38650948, 2024). "Unlike control T cells, which were not activated by either K562 or HCC827 cancer cells, TR4‐CAR‐T cells were activated to secrete TNF‐α and IFN‐γ by HCC827 but not by K562." (PMID 38853761, 2024). "In vitro studies with the use of human NIMBC (nonmuscle-invasive bladder cancer) cancer cell lines showed that BCG increases the production of IL-6 and IL-8, GM-CSF (granulocyte–macrophage colony-stimulating factor), and tumor necrosis factor (TNF)." (PMID 37298677, 2023). "VEGF-A, TNF-α, CCL2, IL-6, and IFN-γ plasma levels were significantly higher in the Cancer TIF1-γ-DM group, especially those without any anticancer treatment, than those in the non-cancer TIF1-γ-DM and HC groups." (PMID 36357631, 2023). "In this study, high levels of plasma VEGF-A, TNF-α, CCL2, IL-6, and IFN-γ in the Cancer TIF1-γ-DM group, particularly those not undergoing any anticancer treatment, were excellent in distinguishing cancer among the anti-TIF1-γ antibody-positive DM patients." (PMID 36357631, 2023). "Although TIM-3, TNF-α, and IFN-γ mRNA levels were relative to lymph nodes metastasis, there were no statistical differences in the cancer tissue and paracancerous tissue (P > 0.05)." (PMID 36865498, 2023). "The subsequent cancer rate per 100 p-y for VDZ was 1.9 (6 patients amongst 37 exposed to VDZ), and it was not statistically different from patients exposed to USK, anti-TNFα, IMM, or no therapy (3.0, 3.8, 1.6, and 2.7, respectively, p = 0.41)." (PMID 36672491, 2023). "In contrast to the effects of TGF β1 as a negative modulator of MHC I expression, TNF-α activates the NF-κB pathway, which stimulates MHC I expression in cancer." (PMID 38067396, 2023). "Significant levels of IL-2, IFN-ɣ and TNF-α were detected in supernatants of CD4+ nfP2X7-M-CAR-T cells co-cultured with MDA-MB-231 and U87 cancer cell lines, but not when co-cultured with either SK-ND-Z or K562 cells." (PMID 37684239, 2023). "In clinical cancer surgical settings, the effect of perioperative NSAID prescription for pain management on the release of TNF-α is not fully discussed." (PMID 36765695, 2023). "Inhibition of both TNFα and MAML1 brought the macrophage-induced MenaINV expression to baseline levels observed when cancer cells were cultured without macrophages." (PMID 37024946, 2023).
cancer (continued). "In contrast, C0008 at the highest concentration resulted in a substantial release of TNFα, MCP-1, and IL6 from PBMCs without target cells at levels 3- to 5-fold lower than in the presence of target cancer cells." (PMID 37067909, 2023). "With regard to TNF-α-induced and MMP-9-dependent fusion of M13SV1-EGFP-Neo breast epithelial cells and human MDA-MB-435 cancer cells, the potential role of β-catenin signaling is not yet clear." (PMID 36555709, 2022). "Importantly, the pathway analysis revealed that the absence of TNF at early time points resulted in the induction of alternative inflammatory pathways, while the genes that significantly modulated at 8 weeks were primarily involved in cancer-related pathways (respectively)." (PMID 36499472, 2022). "This study revealed that EpCAM CAR-T cells secreted cytotoxic cytokines, like tumor necrosis factor-alpha (TNF-α) and IFN-γ and delayed the cancer growth in xenograft models, showing no toxicity in mice." (PMID 39086964, 2022). "When compared to TNFα inhibitors, tofacitinib failed to meet noninferiority criteria for both incidence of cancers and MACE.The study determined that there is indeed a difference in adverse events experienced between users of tofacitinib and TNFα inhibitors." (PMID 36110853, 2022). "In addition, in both cancer cell lines, azilsartan exerted a significant (p < 0.001, p < 0.01) increase in the levels of cleaved caspase 3 protein in non-stimulated and 20 ng/mL TNFα-stimulated cells, respectively, compared to the corresponding untreated cells." (PMID 36431925, 2022). "A persistence of CCGs such as TNF-α, IL-2, and MCP-3 was also observed for exposed cancer patients but not for the healthy control group." (PMID 34830872, 2021). "Out of the TNF apoptosis-inducing ligands, TRAIL is a promising anticancer agent, mainly because of its characteristic of selectively inducing apoptosis in cancer cells while sparing the nontransformed cells." (PMID 33801589, 2021). "D’Agostino and Pearson omnibus normality test indicated that the expression of WNT10A, TNF, and PDGFA in various cancers did not normally distribute." (PMID 32434423, 2020). "Wieder and colleagues reported that T helper 1 cells producing TNF-α and IFN-γ can arrest the cancer cells in a permanently non-proliferating state called senescence." (PMID 32384638, 2020). "In the present study, we showed 20 ng/ml of TNF-α treatment with AIMs, and with or without CDDP, it increased the anti-cancer activities." (PMID 32784919, 2020). "Exercise plays a role in mediating the effects of chronic inflammation, reducing inflammatory markers such as C-reactive protein (CRP), tumor necrosis factor alpha, and various types of interleukin (IL), including IL6, in people with and without cancer." (PMID 31013573, 2019). "Nevertheless, since these results have been reported previously in cancer cells and MAP3K7 was selected from our screen in regular medium without TNF-α stimulation, we set them aside." (PMID 31214512, 2019). "TNFα and IFNγ, the two most studied cytokines in that context, have been shown to enhance MUC16 shedding in some but not all cancer cell lines suggesting also a complex regulation of MUC16 expression that is dependent on the cellular context." (PMID 31039761, 2019). "For example, while neither (mf or cancer cell lines) induces the production of CCL4, TNF-α, IL-10, or VEGF, they both significantly enhance the production of IP-10 and CCL22 in human monocytes." (PMID 29668679, 2018). "No significant changes in the level of IL-1B, TNF-α, and TGF-β1 were observed in co-culture with cancer cells in comparison to monoculture." (PMID 30310111, 2018). "The most interesting finding is that TNF-alpha is directly and significantly regulated by IFNK, a gene that has not been previously related with cancer in literature." (PMID 30458775, 2018).